LINC01089 (long independently transcribed non-coding RNA 1089)
Synonyms: LIMT; AK096174
Gene: Long non-coding RNA gene on chromosome 12 (121,795,267 to 121,803,906, reverse strand). Ensembl gene ENSG00000212694.
Diseases named in the same sentence as LINC01089 in open-access papers:
LINC01089 is named in the same sentence as 22 diseases in open-access papers, as found by Europe PMC text mining. Sharing a sentence is not in itself a finding about the gene and the disease. The quoted sentences say what the papers report.
breast carcinoma (12 papers, 2016 to 2024). "LINC01089 exhibits significantly dysregulated expression in several diseases, including hepatocellular carcinoma, lung cancer, gastric cancer, and breast cancer, and is associated with various clinical features." (PMID 39334363, 2024). "LINC01089 is a highly conserved lncRNA that inhibits cell proliferation and causes metastasis in breast cancer." (PMID 33282723, 2020). "In osteosarcoma, breast cancer, and lung adenocarcinoma cells, overexpression of LINC01089 can promote apoptosis and inhibit cell growth and proliferation." (PMID 39334363, 2024). "Further studies in breast cancer have shown that knocking down LINC01089 promotes the progression of cells from the G1 phase to the S phase by upregulating CDK4 and CDK6 expression, thus shortening the cell cycle." (PMID 39334363, 2024). "LINC01089 acts as a tumor suppressor that inhibits malignant progression capacity in breast cancer, NSCLC, and colorectal cancers." (PMID 36306007, 2022). "LINC01089 is a recently researched lncRNA and it has been uncovered to exert anti-tumor function in breast cancer." (PMID 34281560, 2021). "In breast cancer, LINC01089 overexpression impedes cancer metastasis via regulating Wnt/β-catenin signaling." (PMID 33088215, 2020). "The molecular mechanisms by which LINC01089 regulates breast cancer are diverse and complex." (PMID 39334363, 2024). "LINC01089 has been demonstrated to exert tumor-suppressive effects in various cancers, including colorectal cancer, gastric cancer, lung cancer, ovarian cancer, cervical cancer, papillary thyroid carcinoma, breast cancer, and osteosarcoma." (PMID 39334363, 2024). "LINC01089 can be used as an inhibitor of ECM invasion in breast cancer." (PMID 36447214, 2022). "Although LINC01089 has been revealed to be down-regulated in breast cancer cells, the expression of it in LUAD cells remains unknown." (PMID 34281560, 2021). "LINC01089 has been reported in a limited number of articles (n = 2, PubMed) for a negative association with breast cancer metastasis in part via inhibition of the Wnt/β-catenin signaling." (PMID 33266355, 2020). "Recently, some it has been demonstrated that the lncRNA LIMT (lncRNA inhibiting metastasis, also called LINC01089) inhibits tumor growth in some cancers, including gastric cancer, colorectal cancer, and breast cancer." (PMID 35526240, 2022). "As reported, LINC01089 suppresses the malignant progression of non-small cell lung cancer (NSCLC), breast cancer, and colorectal cancers." (PMID 36306007, 2022). "Taken together, these results indicated that LINC01089 acts as a metastasis-inhibiting marker during NSCLC progression, consistent with the function previously reported in breast cancer." (PMID 33282723, 2020). "LINC01089 (also known as LncRNA Inhibiting Metastasis; LIMT) is an EGF regulated lncRNA which is down-regulated in breast cancer tissues and cell lines, especially in aggressive subtypes of breast cancer." (PMID 33128008, 2020). "Mechanistically, LINC01089 exerts its tumor-suppressive effects by competitively binding to miR-27a-3p, thereby promoting the expression of TET1 and inhibiting the malignant progression of breast cancer." (PMID 39334363, 2024).
gastric cancer (6 papers, 2020 to 2025). A primary or metastatic malignant neoplasm involving the stomach. "Similarly, low levels of LINC01089 in gastric cancer patients are associated with lymphatic metastasis." (PMID 39334363, 2024). "Research indicates that LINC01089 is consistently downregulated in both gastric cancer tissues and cell lines." (PMID 39334363, 2024). "Similarly, LINC01089 inhibits gastric cancer cell growth by targeting miR‐27a‐3p and enhancing TET1 expression, and STARD7‐AS1 has been reported to modulate cell proliferation and autophagy through the miR‐31‐5p/TXNIP." (PMID 40665897, 2025). "However, further research using animal models is needed to validate these findings and fully elucidate the role of LINC01089 in gastric cancer." (PMID 39334363, 2024). "LINC01089 is a tumor-suppressive lncRNA in gastric cancer and lung cancer." (PMID 37081063, 2023). "However, LINC01089 also promotes gastric cancer via sponging miR-145-5p and resistance to sorafenib in hepatocellular carcinoma cells by targeting miR-665." (PMID 35681785, 2022). "Also, LINC01089 is found to be a lncRNA playing tumor-suppressive role in gastric cancer via regulating miR-27a-3p/TET1 axis and can block the proliferation as well as metastasis of colorectal cancer cells through the regulation of miR-27b-3p/HOXA10 axis." (PMID 34281560, 2021).
hepatocellular carcinoma (6 papers, 2022 to 2025). A malignant tumor that arises from hepatocytes. "Expression analyses reveal that LINC01089 is downregulated in nearly all types of malignant tissues, with the exception of hepatocellular carcinoma." (PMID 39334363, 2024). "Intriguingly, in hepatocellular carcinoma tissues, LINC01089 expression has been reported to be both downregulated and upregulated in different studies, with upregulation associated with poor patient prognosis." (PMID 39334363, 2024). "For example, the SE-driven m6A readers IGF2BP2/3 stabilise DDX21 mRNA to facilitate the progression of acute myeloid leukaemia, and the SE-regulated lncRNA LINC01089 induces alternative splicing of DIAPH3 through m6A modification to drive hepatocellular carcinoma progression." (PMID 41436435, 2025). "Interestingly, in different hepatocellular carcinoma animal models, overexpression of LINC01089 has shown contradictory effects: it both attenuates tumorigenesis and metastasis and promotes cancer cell metastasis." (PMID 39334363, 2024). "However, xenograft models of hepatocellular carcinoma have yielded disparate results regarding LINC01089's function." (PMID 39334363, 2024). "This suggests that LINC01089 may have a multifaceted role in hepatocellular carcinoma, acting as a tumor suppressor in some contexts while promoting tumor progression in others." (PMID 39334363, 2024). "Additionally, substantial evidence suggests that LINC01089 exhibits aberrant expression levels in multiple human cancers, such as hepatocellular carcinoma, lung cancer, and gastric tumors." (PMID 39334363, 2024).
lung adenocarcinoma (5 papers, 2020 to 2025). A carcinoma that arises from the lung and is characterized by the presence of malignant glandular epithelial cells. "For instance, LINC01089 is lowly expressed in lung adenocarcinoma tissues, correlating with larger tumor size and poorer histological differentiation." (PMID 39334363, 2024). "In the context of lung adenocarcinoma, overexpression of LINC01089 can counteract the promoting effects of miR-543 on tumor suppressor genes (BMP2 and ADCY6), inhibiting tumorigenesis and promoting apoptosis of tumor cells." (PMID 39334363, 2024). "LINC01089 can also suppress the proliferation and migration of lung adenocarcinoma cells by regulating the miR-301b-3p/STARD13 axis." (PMID 39334363, 2024). "LncRNA LINC01089 inhibits cell proliferation and promotes the apoptosis of lung adenocarcinoma (LUAD) cells via acting as a ceRNA." (PMID 37081883, 2023). "Moreover, a search on the GEPIA database revealed a downregulation of LINC01089 expression in both lung adenocarcinoma and lung squamous carcinoma samples, relative to the adjacent normal tissues." (PMID 33282723, 2020).
colorectal cancer (4 papers, 2021 to 2025). A primary or metastatic malignant neoplasm that affects the colon or rectum. "Apart from the specific cancers discussed earlier, LINC01089 is consistently downregulated in several other malignancies, including cervical cancer (CC), colorectal cancer (CRC) and glioma." (PMID 39334363, 2024).
lung carcinoma (3 papers, 2020 to 2024). "In the present study, we explored the roles of LINC01089 in lung carcinoma progression and unraveled the associated underlying mechanisms." (PMID 33282723, 2020). "Furthermore, reduced levels of LINC01089 are associated with larger tumor sizes and poorer histological differentiation in lung cancer patients." (PMID 39334363, 2024). "The downregulation of LINC01089 promotes the proliferation, migration, and invasion of lung cancer cells." (PMID 39334363, 2024). "Studies have shown that the expression of LINC01089 is significantly reduced in lung cancer tissues compared to adjacent normal tissues." (PMID 39334363, 2024). "Reports indicate that downregulation of LINC01089 can enhance metastasis and in vivo growth of lung cancer." (PMID 39334363, 2024). "Functional biological analyses indicate that LINC01089 can inhibit lung cancer cell migration and invasion." (PMID 39334363, 2024). "According to PAH GRN analysis, IRF9 is capable of regulating LINC01089 expression along with 189 other PAH common DEGs, which are known to be co-expressed in lung cancer models and are related to retromer complex binding." (PMID 39791702, 2024).
non-small cell lung carcinoma (3 papers, 2020 to 2024). A group of at least three distinct histological types of lung cancer, including non-small cell squamous cell carcinoma, adenocarcinoma, and large cell carcinoma. "Overall, these findings underscore the critical role of LINC01089 in the early diagnosis, prognosis evaluation, and treatment of non-small cell lung cancer, indicating its potential as a biomarker and therapeutic target." (PMID 39334363, 2024). "LINC01089 suppresses the malignant progression of breast, colorectal, and non-small cell lung cancers." (PMID 36306007, 2022). "Moreover, silencing LINC01089 not only promotes metastasis but also enhances chemotherapy resistance in non-small cell lung cancer." (PMID 39334363, 2024). "Since EMT is well known as a classic cell phenotype that is frequently involved in the regulation of cancer cell progression, we hypothesized that LINC01089 suppressed non-small cell lung carcinoma EMT progression by sponging miR-27a to target the SFRP1-Wnt/β-catenin pathway." (PMID 33282723, 2020). "Functionally, LINC01089 acts as a miR-27a sponge by elevating SFRP1 expression and modulating the Wnt/β-catenin–EMT pathway to arrest non-small cell lung carcinoma tumorigenesis." (PMID 33282723, 2020).
ovarian carcinoma (3 papers, 2020 to 2025). A malignant neoplasm originating from the surface ovarian epithelium. "In ovarian cancer, LINC01089 is downregulated by M2-like tumor-associated macrophages (TAMs) secreting EGF, which activates the EGFR-ERK signaling pathway." (PMID 39334363, 2024). "In ovarian cancer research, LINC01089 has been implicated in ascites formation." (PMID 39334363, 2024). "Animal experiments have further demonstrated the critical role of LINC01089 in ovarian cancer tumorigenesis." (PMID 39334363, 2024). "Conversely, upregulation of LINC01089 exerts an opposite effect in ovarian cancer and osteosarcoma." (PMID 39334363, 2024).
cervical cancer (2 papers, 2023 to 2024). A primary or metastatic malignant neoplasm involving the cervix. "Similarly, in cervical cancer, LINC01089 also acts as a tumor suppressor by sponging miR-27a-3p to increase the expression of BTG2, thereby inhibiting cell proliferation and metastasis." (PMID 39334363, 2024). "This implies that LINC01089 might influence cervical cancer through miR-27a-3p and BTG2, potentially affecting the Wnt/β-catenin signaling pathway." (PMID 39334363, 2024). "Furthermore, LINC01089, showing low levels in cervical cancer, was reversely correlated with tumor growth and lymph node metastasis as a consequence of sponging miR-27a-3p, and this was reversed by LINC01089 knockdown." (PMID 37190145, 2023).
glioma (2 papers, 2020 to 2024). A benign or malignant brain and spinal cord tumor that arises from glial cells (astrocytes, oligodendrocytes, ependymal cells). "Furthermore, studies have shown that downregulation of LINC01089 expression is associated with poor prognosis in glioma patients." (PMID 39334363, 2024). "Multivariate analysis revealed that decreased LINC01089 expression and high pathological grade for gliomas are independent predictors of poor patient prognosis." (PMID 39334363, 2024). "Moreover, LINC01089 is down-regulated in glioma tissues, and its down-regulation predicts unfavorable prognosis of the patients; additionally, and its restoration impedes the malignant biological behaviors of glioma cells." (PMID 33088215, 2020).
thyroid cancer (2 papers, 2022 to 2024). "Here, the key functions and mechanisms of LINC01089 in the malignant progression of thyroid cancer were studied." (PMID 36306007, 2022). "Clinical investigations have revealed that lower LINC01089 expression correlates with higher tumor staging and regional lymph node metastasis, highlighting the significant potential of LINC01089 as a prognostic marker for thyroid cancer." (PMID 39334363, 2024). "Furthermore, LINC01089 overexpression effectively blocked thyroid cancer cell proliferation, migration, and invasion." (PMID 36306007, 2022). "Similarly, our study found that LINC01089 overexpression blocked the malignant progression capacity of thyroid cancer, verifying that LINC01089 also acts as a tumor suppressor." (PMID 36306007, 2022). "In addition, the function of LINC01089 in thyroid cancer needs to be further verified at the animal level." (PMID 36306007, 2022). "Moreover, LINC01089 expression was lower in thyroid cancer cells (TPC-1 and CAL-62) compared with that in normal Nthy-ori 3-1 cells." (PMID 36306007, 2022). "miR-27b-3p overexpression successfully weakened the LINC01089 effect in thyroid cancer." (PMID 36306007, 2022). "However, the role of LINC01089 in thyroid cancer requires further validation in animal models, and given the limited number of thyroid cancer patients who experience metastasis and mortality, the relationship between LINC01089 expression and recurrence or death remains to be further explored." (PMID 39334363, 2024). "Therefore, we hypothesized that miRNAs might be sponged by LINC01089, which prevents the progression of thyroid cancer." (PMID 36306007, 2022). "Whether FBLN5 acts downstream of LINC01089 regulation in thyroid cancer is unclear." (PMID 36306007, 2022). "Combined with the regulatory relationship between miR-27b-3 and FBLN5 and the adsorption relationship between LINC01089 and miR-27b-3p, these results suggested that LINC01089 upregulates the expression of FBLN5 by adsorbing miR-27b-3p and exerts a tumor suppressor function in thyroid cancer." (PMID 36306007, 2022). "In conclusion, LINC01089 plays a tumor-suppressive role by binding miR-27b-3p to increase FBLN5 expression, confirming that LINC01089 has tremendous potential to become a therapeutic target for thyroid cancer treatment." (PMID 36306007, 2022). "In conclusion, LINC01089 plays a tumor-suppressive role in malignant progression by inhibiting miR-27b-3p and increasing FBLN5 protein, confirming that LINC01089 has tremendous potential for use in the treatment of thyroid cancer." (PMID 36306007, 2022). "However, the function of LINC01089 in thyroid cancer has not yet been elucidated." (PMID 36306007, 2022).
hepatitis c infection (1 paper, 2024). "IRF9 and LINC01089 in pulmonary arterial hypertension are related to the regulation of signaling pathways like MAPK, NOTCH, human papillomavirus, and hepatitis c infection." (PMID 39791702, 2024).
small cell lung carcinoma (1 paper, 2024). Small cell lung cancer (SCLC) is a highly aggressive malignant neoplasm, accounting for 10-15% of lung cancer cases, characterized byrapid growth, and early metastasis. "Recent studies in small cell lung cancer (SCLC) revealed that LINC01089 knockdown mediated changes in the expression of N-cadherin, E-cadherin, Snail, Slug, and SRPR1 in A549 and H1299 cells, with protein levels of p-GSK-3β and β-catenin also increased following siLINC01089 transfection." (PMID 39334363, 2024).